PAK1 (p21 (RAC1) activated kinase 1)
Diseases named in the same sentence as PAK1 in open-access papers (continued):
Sharing a sentence is not in itself a finding about the gene and the disease.
melanoma (continued). "Indeed, such strategies to exploit cell cycle checkpoint deficiencies, albeit not in a PAK1-dependent manner, have been proposed for melanoma already." (PMID 37830586, 2023). "Therefore, PAK1 was responsible for LINC00467-induced melanoma deterioration." (PMID 36987414, 2023). "There is evidence that PAK1 isoforms may be functionally distinct and that in melanoma, the predominant splicing pattern favors the creation of an enzymatically active PAK1 over a product of alternative splicing that encodes a truncated kinase domain (Isoform 2)." (PMID 37830586, 2023). "They reported elevated phospho-PAK1/2 levels and AKT pathway activation in RAC1P29S-expressing melanoma cells." (PMID 41034404, 2025). "PAK1 is an oncogene that is involved in activation of the MAPK pathway, and has been suggested as a potential target in BRAF–wild type melanomas." (PMID 38758740, 2024). "The most recurrently affected TAD boundary in both acral (n = 27; 23%) and mucosal (n = 7; 11%) melanomas was chr11:77750000–77825000, which is adjacent to TADs containing the cancer genes GAB2 and PAK1." (PMID 38758740, 2024). "Interestingly, a study in melanoma cells suggested that PAK1 regulated invadopodia formation, intriguingly via the same Ser113 phosphorylation site as Moshfegh and colleagues reported, sparking debate over whether PAK1-regulation of invadopodia actin dynamics is cancer-type specific." (PMID 35385780, 2022). "Among these kinases, 6 (RPS6KB2, DSTYK, TBRG4, CDK4, POLR2E, FASTKD5) and 4 (STK26, PAK1, EPHB2 and JAK3) were consistently up- or down-regulated, respectively, in the metastatic lines of at least two pairs of melanoma cells." (PMID 32051510, 2020). "JMJD6 was found to increase the PAK1-full/PAK1Δ15 ratio, to enhance MAPK signaling and to promote proliferation and invasion of melanoma cells." (PMID 31748572, 2019). "PAK‐1 expression was also relatively lower in MDA‐435 cells, which are a melanoma‐derived cell line." (PMID 31516713, 2019). "In the current study, we demonstrated that JMJD6 promotes EMT and metastasis in melanoma, and we showed that JMJD6 does so, through its lysyl hydroxylase activity and via its regulation of the alternative splicing of PAK1." (PMID 29187213, 2017). "Given our observations that JMJD6 regulates the alternative splicing of PAK1 and influences the MAPK signaling in melanoma cells, it is conceivable that JMJD6 is also involved in the regulation of EMT and metastasis in melanoma." (PMID 29187213, 2017). "Given our observations that JMJD6 influences, via regulation of PAK1 alternative splicing, multiple cellular processes in melanoma cells, understanding the aberrant regulation of JMJD6 in melanomas is of great significance." (PMID 29187213, 2017). "In support of the regulation of PAK1 thus the MAPK signaling by JMJD6, our experiments also revealed that JMJD6 regulates melanogenesis and angiogenesis in melanoma cells." (PMID 29187213, 2017). "To further explore the functional significance of the regulation of the alternative splicing of PAK1 by JMJD6 and to substantiate the role of JMJD6 in melanoma carcinogenesis, we next investigated the effect of JMJD6 on the proliferation of melanoma cells." (PMID 29187213, 2017). "Activated c-Jun transactivates JMJD6, which, in turn, through regulation of the alternative splicing of PAK1, enhances the MAPK signaling and drives melanoma carcinogenesis." (PMID 29187213, 2017). "Previous studies have documented that PAK1 is amplified in BRAF wild type tumors and identified PAK inhibitors as agents that can slow the growth of melanoma xenografts and synergize with BRAF inhibitors to kill melanoma cells." (PMID 28753606, 2017). "Meanwhile, the level of the exon-skipped PAK1 mRNA isoforms, PAK1Δ15, was significantly elevated in JMJD6-depleted melanoma cells." (PMID 29187213, 2017). "This study clearly demonstrates that PAK1 and PAK4 play an important role in melanoma cell invasion." (PMID 27765920, 2016).
melanoma (continued). "In this study we demonstrate that PAK1 and PAK4 expression at the protein level is significantly increased in melanoma compared to melanocyte controls using both cell lines and patient derived cell strains." (PMID 27765920, 2016). "We found that depleting either PAK1 or PAK4 significantly reduced invadopodia maturation and subsequent matrix degradation in melanoma cells and found that PAK1 or PAK4 expression are required for efficient invasion in 3D and in vivo invasion assays." (PMID 27765920, 2016). "This study used the invadopodia assay as an indicator of invasive potential, alongside a 3D and an in vivo invasion assay, to investigate the role of PAK1 and PAK4 in melanoma invasion." (PMID 27765920, 2016). "PAK1 and PAK4 protein levels were elevated in invasive melanoma cell lines and cells derived from patient samples." (PMID 27765920, 2016). "Taken together our work points to essential requirements for both PAK1 and PAK4 during melanoma invasion and further provides clear evidence of differential function." (PMID 27765920, 2016). "PAK1 and GAB2 were well known regulators of the MAPK pathway and might participate in the regulation of melanoma development and response to therapies." (PMID 35844619, 2022). "Thus, the regulation of PAK1 alternative splicing by JMJD6 would have significant consequences on the MAPK signaling and cellular processes of melanoma cells." (PMID 29187213, 2017). "Indeed, we showed that ectopic expression of JMJD6 promoted the proliferation of melanoma cells, an effect that was dependent on the lysyl hydroxylase activity of JMJD6 and was through the regulation of the alternative splicing of PAK1." (PMID 29187213, 2017). "Though possibly the case for primary melanoma, our study has shown that this is not the case when investigating metastatic melanoma, where PAK1 overexpression correlates with invasion (rather than BRAF mutational status)." (PMID 27765920, 2016). "Further studies in melanoma also supported a role for PAK1-dependent invadopodia formation, whereby PAK1-depleted melanoma cells could not initiate actin puncta." (PMID 35385780, 2022). "Our results suggest that both PAK1 and PAK4 could play a role during melanoma invasion." (PMID 27765920, 2016). "Interestingly one recent report showed that the CDC42 homologue RhoJ and its effector PAK1 modulate ATR activity via degradation of claspin after DNA damage thereby uncoupling ATR from Chk1; moreover RhoJ appears to be upregulated in advanced melanoma." (PMID 24416382, 2014). "However, our PAK RNAi experiments suggest that inhibiting PAK1 alone may not be sufficient to overcome BRAFi/MEKi resistance in BRAF V600-mutant melanoma." (PMID 41109929, 2025). "However, splicing variations related to cancer have not been reported for any of these genes except PAK1, for which a JMJD6-regulated exon inclusion event altering the PKC domain enhances MAPK signaling in melanoma." (PMID 35581644, 2022).
lung carcinoma (40 papers, 2011 to 2025). "Elevated PAK1 levels have been associated with various malignancies, including breast, colon, ovarian, hepatic, pancreatic, glioma, colorectal, prostate, and lung cancers or T-cell lymphoma." (PMID 41516310, 2025). "Our findings showed that PAK1 mRNA overexpression was associated with poor overall survival in patients with lung cancer (hazard ratio (HR), 1.28; p = 0.00011, log-rank test)." (PMID 33261184, 2020). "Perhaps, the functional polymorphisms in the PAK1 gene (rs2154754) are responsible for the significant influence of smoking levels on lung cancer risk." (PMID 33261184, 2020). "In summary, presented data introduce KRAS/PAK1/Crk axis as one of the prominent signaling pathways downstream of mutated KRAS in lung cancer." (PMID 25956913, 2015). "In summary, our study investigated the role of genetic variants in PAK1 gene in lung cancer development in a Chinese population." (PMID 26377044, 2015). "Of interest, PAK1 was frequently implicated in the tumorigenesis 15,16 and up-regulation of PAK1 was frequently detected in various human cancers including lung cancer 16–19." (PMID 26377044, 2015). "In our present study, we evaluated the association of four potentially functional polymorphisms in the PAK1 with lung cancer risk in a case–control study including 1341 cases and 1982 controls in a Chinese population." (PMID 26377044, 2015). "Notably, epidermal growth factor receptor (EGFR) mutation-positive lung cancer patients with high PAK1 expression showed higher mortality rates than those with low PAK1 expression (91.3% vs. 62.5%, p = 0.02)." (PMID 33261184, 2020). "Our results suggested, for the first time, that genetic variants in PAK1 may modify the risk of lung cancer." (PMID 26377044, 2015). "We further evaluated whether PAK1 overexpression would be associated with a greater number of patients with lung cancer using a Kaplan–Meier plotter, which contained information from 1925 patients with lung cancer derived from data available in the PAK1 Affy database (ID: 202161_at)." (PMID 33261184, 2020). "Therefore, PAK1 overexpression could serve as a molecular target for the treatment of EGFR mutation-positive lung cancer, especially among male patients and current/former smokers." (PMID 33261184, 2020). "However, the role of genetic variants in PAK1 on the development of lung cancer is still unclear." (PMID 26377044, 2015). "We hypothesized that functional polymorphisms in PAK1 gene may modify the risk of lung cancer." (PMID 26377044, 2015). "In lung cancer, PAK1 promotes inhibitors resistant to tyrosine kinase (Gefitinib and Erlotininb) in both wild-type EGFR and mutant cells." (PMID 36830998, 2023). "In an in vivo experiment, an inhibitor of PAK1 reduced the tumor size in a murine lung cancer model." (PMID 38188678, 2023). "Following radiation to lung cancers, PAK1 can be phosphorylated by JAK2 at critical residues of tyrosine, instead of serine/threonine, to maintain protein stability and enhance nuclear translocation." (PMID 37564209, 2023). "IL-1β and PAK1 are known to increase migration and invasion in various cancer cells, including lung cancer, which is consistent with our results." (PMID 38188678, 2023). "Lung cancer: PAK1 provides resistance to tyrosine kinase inhibitors in both wild-type epidermal growth factor receptor (EGFR) and mutant cells." (PMID 36830998, 2023). "The nuanced difference in the mode of PAK1 phosphorylation between myxofibrosarcomas and irradiated lung cancers is probably cellular context-dependent." (PMID 37564209, 2023). "Here, we found that PAK1 plays a key role in the IL-1β–induced migration and invasion of lung cancer cells." (PMID 38188678, 2023). "PAK1 tyrosine phosphorylation is necessary to induce epithelial–mesenchymal transition and radioresistance in lung cancer cells." (PMID 35500159, 2022). "We identified a CD44/PAK1/AKT signaling axis as a commonly occurring resistance mechanism to FGFR1 inhibition in lung cancer." (PMID 35853934, 2022).
lung carcinoma (continued). "Co-inhibition of CD44, Pak1 or AKT together with FGFR1 (re-)sensitized resistant lung cancer cells to FGFR1-targeted therapy." (PMID 35853934, 2022). "The reported anti-tumor effect of Rac1 and Pak1 inhibitors in lung cancer models and the evidence for enhanced Pak1 activation in lung cancer are strong indicators of Rac1 hyperactivation." (PMID 32158759, 2020). "Our study on lung cancer cell lines and bioinformatic analysis showed that PAK1 expression differed based on sex and exhibited a correlation with lung fibrosis associated with the protease-activated receptor 2 pathway (data not shown)." (PMID 33261184, 2020). "PAK1 inhibition was observed to induce cell cycle arrest via the accumulation of lung cancer cells in the G1 phase, and significantly impair tumor growth in lung cancer xenograft models, indicating that PAK1 drives NSCLC tumor proliferation." (PMID 33261184, 2020). "We therefore analyzed the activity of the Rac signaling pathway in our panel of lung cancer cells by measuring levels of phosphorylated Pak1 in glucose-depleted cells." (PMID 30609754, 2019). "Amount evidence has indicated that PAK1 is substantially overexpressed in various cancers, including breast cancer, hepatocellular carcinoma, pancreatic cancer, lung cancer and cutaneous T cell lymphoma." (PMID 30971268, 2019). "In A549 lung cancer cells, the resistance was downregulated by macropinocytosis inhibition or siRNA knockdown of PAK1, an essential macropinocytosis enzyme." (PMID 29152126, 2017). "Among tested compounds, labdadiene showed the strongest inhibitory activity against the PAK1-dependent growth of A549 lung cancer cells with an IC50 of 67 μM." (PMID 28098826, 2017). "In the Bhattacharjee lung cancer database, Pak1 upregulation was observed to be nearly 12-fold, and in the Hou and Stearman lung cancer databases, Pak1 was upregulated 3- and 2.2-fold, respectively." (PMID 26555075, 2015). "Our previous work showed that PAK1 phosphorylates adaptor protein Crk on serine 41 which in turn increases motility and invasiveness of lung cancer cells." (PMID 25956913, 2015). "These evidence collectively revealed the importance of PAK1 in carcinogenesis, especially lung cancer." (PMID 26377044, 2015). "We subsequently examined the effect of RNAi-mediated knockdown of PAK1 in a panel of lung cancer cell lines to clarify the contribution of PAK1 towards tumor cell growth and survival." (PMID 21653999, 2011). "Cytoplasmic p120ctn activated by ERK through PAK1 promotes drug resistance in lung cancer cells." (PMID 36830998, 2023). "However, to the best of our knowledge, no clinical study has directly related lung cancer metastasis with TonEBP and PAK1 in patients with lung cancer, and this is an issue that warrants further investigation." (PMID 38188678, 2023). "Inhibition of migration and invasion of lung cancer cells via Rac1/PAK1 signaling pathway." (PMID 37191432, 2023). "Importantly, PAK1 acts as a potential EMT inducer by stimulating Vimentin expression, thereby inducing E-cadherin loss in lung cancer cells." (PMID 37225681, 2023). "More importantly, PAK1 has been reported to promote gefitinib resistance in lung cancer cells." (PMID 36059806, 2022). "Our findings suggest that the LCAT1-miR-4715-5p-RAC1/PAK1 axis could be a valuable target for lung cancer prognosis and therapies." (PMID 31779616, 2019). "LCAT1–miR-4715-5p–RAC1/PAK1 axis plays an important role in the progression of lung cancer." (PMID 31779616, 2019). "Recently, PAK1 phosphorylation was confirmed to confer radio-resistance in lung cancer cells." (PMID 27713506, 2016). "In special, for lung cancer PAK1 could promote cell motility, tumor migration, and invasion through different mechanism 20,21." (PMID 26377044, 2015). "Here we sought to investigate whether PAK1, Crk, p120-catenin and E-cadherin establish a correlation with each other in clinical lung cancer specimens." (PMID 25956913, 2015).
lung carcinoma (continued). "Notably, PAK1 kinase can promote lung cancer cell motility, tumor migration, and invasion through activation of PAK1/LIMK1/cofilin pathway and CRK-II serine phosphorylation 20,21." (PMID 26377044, 2015). "Collectively, our phosphoproteomic analysis of lung-cancer cells resistant to FGFR1 inhibitor provides a large data library of resistance-associated phosphorylation patterns and leads to the proposal of a common resistance pathway comprising CD44, PAK1 and AKT activation." (PMID 35853934, 2022). "In addition, RT induces expression of Ras related C3 botulinum toxin substrate 1 (RAC1), a member of the Rho family GTPase which promotes cell division via cell cycle, and enhances radioresistance via p21-activated kinase 1 (PAK1)-LIM kinase 1 (LIMK1)-Cofilins signaling in lung cancer." (PMID 33419318, 2020). "Therefore, targeting PAK1 using PAK1 inhibitors might be a potential therapeutic strategy for treating EGFR-mutant lung cancer, especially among male smokers." (PMID 33261184, 2020). "Our current study provided genetic evidence at the population level that PAK1 may be involved in the carcinogenesis and development of lung cancer and further highlighted the important role of genetic variants in PAK1 as molecular biomarkers for lung cancer susceptibility." (PMID 26377044, 2015). "In support, tyrosyl phosphorylation of PAK1 by JAK2 increased PAK1-mediated Snail phosphorylation and induced EMT in response to irradiation of lung cancer cells." (PMID 38660565, 2024). "Co-inhibition of AKT/FGFR1, CD44/FGFR1 or PAK1/FGFR1 sensitized ‘intrinsically resistant’ and ‘induced-resistant’ lung-cancer cells synergetically to FGFR1 inhibition." (PMID 35853934, 2022). "Silencing Rac1 significantly inhibited the EMT phenotype in lung cancer cells, accompanied with a significant down-regulation of RAC1, PAK1, p-PAK1, LIMK1, p-LIMK1, Cofilin, and p-Cofilin in lung cancer cells." (PMID 32411607, 2020). "Third, patients with high PAK1 expression and EGFR mutant lung cancer showed poor prognosis and survival." (PMID 33261184, 2020). "In the present study, we found that IR promoted lung cancer cell EMT in the process, accompanied with an up-regulation of RAC1, PAK1, p-PAK1, LIMK1, p-LIMK1, Cofilin, p-Cofilin in these cells." (PMID 32411607, 2020). "Consistent with the results of recent studies, which showed that PAK1 expression was upregulated in lung cancer compared to that in adjacent healthy bronchial tissues, we found that NSCLC specimens had higher PAK1 levels than healthy bronchial cells." (PMID 33261184, 2020). "Others hold MASPIN inhibits cell motility by suppressing Rac1 and PAK1 activity, promotes cell adhesion via the PI3K/ERK pathway, and suppresses survival of lung cancer cells through modulation of AKT pathway." (PMID 32391558, 2020). "Consistently, phosphorylated PAK1 expression was downregulated in both the miR-4715-5p overexpressed and the LCAT1 knockdown lung cancer cells." (PMID 31779616, 2019). "Mechanistic characterization revealed that this drug combination abrogated expression and activation of membrane receptors and downstream signaling proteins crucial in lung cancer: EGFR, MET, PAK1, PKCι, ERK1/2, AKT, YAP1 and mTOR." (PMID 31660987, 2019). "A recent study stated that PAK1 promotes epithelial–mesenchymal transition (EMT) and radio-resistance in lung cancer cells." (PMID 30971268, 2019). "Our research has centered on targeting PKCι-PAK1 signaling and was effective with auranofin plus OTSSP167 in 3 lung cancer models in vitro and in vivo." (PMID 31660987, 2019). "MiR-98-5p was significantly increased and promoted cell proliferation and invasion in lung cancer by directly targeting TWIST, PAK1, and ITGB3." (PMID 29970191, 2018). "This JAK2-mediated PAK1 tyrosyl phosphorylation strengthens the transcriptional repression activity of snail to mediate epithelial-mesenchymal transition and radioresistance, while PAK1Y3F mutant nullifies these effects in irradiated lung cancers." (PMID 37564209, 2023).